NQO1 (NAD(P)H quinone dehydrogenase 1)
Diseases named in the same sentence as NQO1 in open-access papers (continued):
Sharing a sentence is not in itself a finding about the gene and the disease.
COVID-19 (6 papers, 2021 to 2026). A disease caused by infection with severe acute respiratory syndrome coronavirus 2. "Among the genes included in these pathways, we found NQO1, CAT, RETSAT, NDUFS3, and HSD3B7, which were all already found associated with COVID-19 severity from our gene-based burden test analysis." (PMID 41500120, 2026). "In viral infections such as COVID-19, dysregulation of either system—overactive NOX or underactive NQO1 (due to genetic polymorphisms)—can lead to excessive inflammation and tissue injury." (PMID 41209585, 2025). "The enzyme NQO1 plays a critical protective role in mitigating OS and inflammation during viral infections, including COVID-19." (PMID 41209585, 2025). "Notably, polymorphisms in NQO1, such as C609T (rs1800566) and 465 (C>T) in the human cDNA sequence, lead to reduced or absent enzyme activity, compromising cellular antioxidant capacity and potentially exacerbating the cytokine storm and lung injury observed in severe COVID-19 cases." (PMID 41209585, 2025). "We further found that the NQO1 expression level was positively correlated with both the disease severity of COVID-19 patients and virus copy levels in cultured AECs." (PMID 37301869, 2023). "There was not any any studies showing that NQO1 levels in serum are associated with COVID-19 mortality or disease severity." (PMID 41209585, 2025). "In addition, DCM treatment downregulated NQO1 expression and disrupted signalling pathways associated with SARS-CoV-2 disease outcomes (e.g., Endocytosis and COVID-19 signalling pathways) in cultured AECs." (PMID 37301869, 2023). "There is emerging evidence, however, that NQO1 expression may be altered post–COVID-19 in the context of neuroinflammatory processes, but this relates to post-infection neurological effects rather than serving as a prognostic blood biomarker during acute COVID-19." (PMID 41209585, 2025). "NQO1 expression levels showed a significant positive correlation with the severity of COVID-19 in patients and virus copies in cultured AECs; Also, DCM treatment can attenuate NQO1 expression." (PMID 37301869, 2023). "Transcriptome analysis of severe COVID-19 patients has shown that NRF2 dependant genes are suppressed including Heme Oxygenase 1 (HMOX1) and NAD(P)H Quinone Dehydrogenase 1 (NqO1)." (PMID 34240083, 2021). "Biopsies from COVID-19 patients showed that genes associated with the NRF2-dependent antioxidant response, such as NQO1, PPAR-γ and HO-1, were decreased, suggesting that NRF2 activation could be a therapeutic strategy for COVID-19." (PMID 36671034, 2023). "Having revealed the expression profile of DCM’s targets (NQO1 and VKORC1) in AECs, we then explored whether the NQO1 and VKORC1 expressions in AECs correlated with the COVID-19 severity in clinical patients." (PMID 37301869, 2023). "Notably, in the context of severe COVID-19, a transcriptomic analysis of lung biopsies from patients revealed the suppression of the NRF2 pathway in response to SARS-CoV-2 infection, marked by the reduced expression of HO-1 and NQO1, which are proteins regulated by NRF2." (PMID 40227198, 2025).
endothelial dysfunction (6 papers, 2017 to 2024). In vascular diseases, endothelial dysfunction is a systemic pathological state of the endothelium (the inner lining of blood vessels) and can be broadly defined as an imbalance between vasodilating and vasoconstricting substances produced by (or acting on) the endothelium. "Sinapic acid alleviated endothelial dysfunction by enhancing HO-1, NQO-1, GCLC, p-Akt, and p-eNOS expression levels, as well as activating Nrf2 nuclear translocation." (PMID 36234721, 2022). "Cinnamaldehyde is suggested to alleviate endothelial dysfunction in response to high glucose by upregulation of NQO1." (PMID 28587104, 2017). "Specifically, the heme oxygenase-1 (HO-1), NADPH quinone oxidoreductase (NQO-1), glutamate-cysteine ligase catalytic subunit (GCLC), Phospho-Akt (p-Akt), and Phospho-eNOS (p-eNOS) expression levels were enhanced by sinapic acid, easing endothelial dysfunction." (PMID 38611326, 2024). "Phenolic extracts derived from RB down-regulated the expression of four genes, ICAM1, CD39, CD73 and NOX4 and up-regulated the expression of another four genes, Nrf2, NQO1, HO1 and eNOS, indicating an antioxidant/ anti-inflammatory effect for RB against endothelial dysfunction." (PMID 31547608, 2019).
fibrosarcoma (6 papers, 2019 to 2025). A malignant mesenchymal fibroblastic neoplasm affecting the soft tissue and bone. "The relative mRNA expression levels of selenoprotein W (SELENOW), SEPP1, masculoaponeurotic fibrosarcoma K (MafK), CAT, SOD1, SOD2, and NAD (P)H: quinone oxidoreductase 1 (NQO1) genes in TN + SeNPs-AOS group were higher than TN group (p < 0.05)." (PMID 38001826, 2023). "Nuclear Nrf2 heterodimerizes with musculoaponeurotic fibrosarcoma (Maf) to recognize ARE and promote the transcription of antioxidant genes, including Nrf1, HO–1, and NQO1." (PMID 36678511, 2022). "In response to stress, Nrf2 binds to the ARE present in gene promoters, with the small musculoaponeurotic fibrosarcoma (sMaf) as a partner, and induces antioxidant enzymes, such as HO-1, GPX, CAT, and NQO-1." (PMID 32916869, 2020).
gastric adenocarcinoma (6 papers, 2012 to 2023). "In our previous study, we found that high level of NQO1 protein significantly associated with shortened survival of patients with gastric adenocarcinoma." (PMID 24499631, 2014). "The chromosome instability (CIN) type had the highest stomach adenocarcinoma’s NQO1 mRNA expression." (PMID 37583897, 2023).
head and neck cancer (6 papers, 2011 to 2024). A primary or metastatic malignant neoplasm affecting the head and neck. "However, polymorphism in the NQO1 gene has been reported to be associated with an increased risk of various cancers such as breast, lung, gastric and head and neck cancer." (PMID 28983331, 2015). "β-lapachone is bioactivated by NAD(P)H:quinone oxidoreductase-1 (NQO1), causing futile oxidoreduction that generates high levels of superoxide, and is currently under clinical investigation, as a monotherapy or in combination with gemcitabine, in patients with pancreatic and head-and-neck cancer." (PMID 22072940, 2011). "The compounds containing the 1,4-quinone moiety interact with NQO1, which is overexpressed in many types of cancer, such as lung, brain, breast, and head and neck cancers." (PMID 39456992, 2024). "The potential goal of therapy can be DT-diaphorase (NQO1), which occurs at high levels in many types of human cancer, such as lung, breast, skin, and head and neck cancer." (PMID 39456992, 2024). "Combining ß-lapachone with XRCC1 knockdown or methoxyamine (MeOX), an apyrimidinic/apurinic (AP)-modifying agent, led to NQO1-dependent synergistic killing in PDA, NSCLC, breast and head and neck cancers." (PMID 26602448, 2015). "In 2017, it was reported that the LD50 of β-lapachone did not correlate with NQO1:CAT in head and neck cancer." (PMID 36978989, 2023).
injury (6 papers, 2019 to 2024). Damage inflicted on the body as the direct or indirect result of an external force, with or without disruption of structural continuity. "Treated groups with L-carnitine showed upregulation of Nrf2/Keap1/NQO1 expression which proposed that Nrf2/Keap1/NQO1 activation is implicated in the therapeutic effect of L-carnitine against acute lung injury." (PMID 34169163, 2021). "Administration of Cur is known to upregulate protein expression levels of both HO-1 and NQO1 in a mouse model with traumatic brain injury and ameliorate secondary issues associated with injury such as oxidative stress." (PMID 31323999, 2019). "Animal study also proved that upregulated NQO-1 expression was correlated with reduced oxidative stress and improved neurological status in rats following traumatic brain injury." (PMID 35993019, 2022).
liver disease (6 papers, 2013 to 2025). "Our results have also shown that NQO1 is also associated with psychiatric disorders, hematological disorders, liver disease, and kidney injury." (PMID 37583897, 2023). "In this study, a TGF-β-induced liver disease model with DIM as an intervention was used to observe expression levels of Nrf2 and its downstream products NQO1 and HO-1 after treatment with different concentrations of DIM." (PMID 36232707, 2022).
multiple sclerosis (6 papers, 2014 to 2024). A progressive autoimmune disorder affecting the central nervous system resulting in demyelination. "We showed that Th17-mediated inflammation was ameliorated in NQO1-deficient EAE model, indicating that inhibition of NQO1 by specific inhibitor such as dicoumarol could be a potential candidate for the therapeutic treatment against autoimmune diseases such as multiple sclerosis." (PMID 35905076, 2022). "NQO1 is strongly upregulated in lesions of post-mortem multiple sclerosis brain, predominantly in astrocytes and some macrophages and oligodendrocytes, whereas elevated NQO1 in neurons is rare." (PMID 28820437, 2017). "NQO1 and peroxiredoxin 2 are also strongly upregulated in lesions of post-mortem multiple sclerosis brain." (PMID 28820437, 2017).
pancreatic adenocarcinoma (6 papers, 2012 to 2024). "The NQO1 mRNA expression levels were significantly associated with the pathological stages in pancreatic adenocarcinoma, thyroid carcinoma, pan-kidney cohort, invasive breast carcinoma, and kidney chromophobe." (PMID 37583897, 2023). "NRF2 is a transcription factor over-expressed in pancreatic adenocarcinomas, which regulates expression of many redox enzymes, including NQO1." (PMID 37446864, 2023). "The NQO1 protein expression level in invasive breast carcinoma, ovarian serous cystadenocarcinoma, and pancreatic adenocarcinoma was verified by pathological tissue from the Department of Pathology of the First Affiliated Hospital of Soochow University." (PMID 37583897, 2023). "Immunofluorescent staining of the human pancreatic adenocarcinoma cell line BxPc-3 for NQO1 revealed that NQO1 is located primarily in the cytosol of these cells." (PMID 22984577, 2012). "In addition, the NQO1 methylation levels were significantly lower in uterine carcinosarcoma, liver hepatocellular carcinoma, pancreatic adenocarcinoma, bladder urothelial carcinoma, bladder urothelial carcinoma, and lung squamous cell carcinoma." (PMID 37583897, 2023). "The association of NQO1 with the mitotic spindles was observed in many different human cell lines including nontransformed cells (astrocytes, HUVEC) immortalized cell lines (HBMEC, 16HBE) and cancer (pancreatic adenocarcinoma, BXPC3)." (PMID 22984577, 2012). "We explored the expression of several antioxidants (NRF2, GPX2, SOD1,2) and NRF2 target genes (NQO1, HMOX1, TXN) in 179 tumors and 171 normal tissues from the TCGA/GTEx pancreatic adenocarcinoma (PAAD) dataset." (PMID 38782891, 2024).
renal fibrosis (6 papers, 2012 to 2025). A final common manifestation of a wide variety of chronic kidney diseases characterized by glomerulosclerosis and tubulointerstitial fibrosis. "Moreover, STZ-treated Nqo1 KO mice showed that NQO1 deficiency aggravated renal fibrosis by dysregulating autophagy." (PMID 33672316, 2021). "In CKD models, Nrf2 activity is suppressed, leading to reduced expression of heme o1xygenase-1 (HO-1), SOD, and NADPH:quinone oxidoreductase 1(NQO1), and contributing to oxidative injury, inflammation, and renal fibrosis." (PMID 40868936, 2025). "The present study has demonstrated that defective expression of the redox signal NQO1 leads to the dysregulation of autophagy and results in exacerbation of DN-related renal fibrosis." (PMID 33672316, 2021). "A growing body of evidence indicates that reactive oxygen species (ROS) mediate TGF-β-induced renal fibrosis, while Nrf2 target genes, such as NQO1 and HO-1, prevent ROS-induced renal fibrosis." (PMID 23056222, 2012). "Under the HG stress, the present enhanced NQO1 expression might be enhanced to counteract HG induced oxidative stress and worsen renal fibrosis." (PMID 33672316, 2021). "Considering that renal fibrosis in our study was further attenuated on day 7 than it was on day 3, late upregulation of NQO1 and Hsp70 might have synergistic effects on the suppression of progressive fibrosis resulting from UUO." (PMID 24393202, 2014). "Moreover, NRF2 activation enhances the antioxidant capacity of cells by upregulating the expression of HO-1/NQO1, reduces renal fibrosis by downregulating the expression of TGF-β1-dependent profibrotic signals, and ultimately improves renal function and slows down HN progression." (PMID 37237889, 2023). "In addition, renal fibrosis progressed further in STZ-treated Nqo1 KO mice." (PMID 33672316, 2021). "This implies that renal fibrosis is aggravated in absence of NQO1." (PMID 33672316, 2021).
Sepsis (6 papers, 2017 to 2023). Sepsis is defined as life-threatening organ dysfunction caused by a dysregulated host response to infection. "The NQO1 antagonist Vatiquinone (EPI-743) has been found to inhibit ferroptosis, a process associated with tissue injury, including in sepsis." (PMID 32736569, 2020). "NQO1, GPX-1, and GSTs mRNA levels were enhanced in DJ-1KO hearts compared with WT following CLP-induced sepsis." (PMID 36978809, 2023). "The effects of MitoQ on sepsis-mediated Nrf2, GCLM, NQO-1, and HO-1 levels were measured via real-time PCR assay." (PMID 32351320, 2020). "In PBMCs and monocytes from sepsis patients, CDDO-Me(bardoxolone methyl) treatment did not reduce LPS-induced Il-6 transcript accumulation although there was target engagement as measured by elevated expression of Nqo-1." (PMID 28886135, 2017).
viral infection (6 papers, 2019 to 2025). "Our data indicated that the virus infection altered the protein expression of Nrf2, HO-1, and NQO1 with diverse kinetics prior to 16 h after infection." (PMID 31687081, 2019). "Therefore, the virus-productive infection kinetics supported the finding that the virus infection modulated the protein expression of Nrf2, HO-1, and NQO1." (PMID 31687081, 2019). "Olagnier and colleagues identified NRF2 as the major factor affected by virus infection and replication, leading to the suppression of NRF2-inducible proteins HO-1 and NAD(P)H quinone oxidoreductase-1 (NqO-1)." (PMID 37853388, 2023).
colon adenocarcinoma (5 papers, 2014 to 2024). "For an in vivo assessment of the efficacy of CBK77 against tumors, we selected the human colon adenocarcinoma cell line LS174T, which expresses functional NQO1 at a comparable level to the MelJuSo cell line used in the high-content screen." (PMID 34615851, 2021).
colorectal adenoma (5 papers, 2010 to 2025). An adenoma that arises from the colon or rectum. "On the other hand, homozygotes of the NQO1 187Ser allele was associated with a 2-fold increase in the prevalence odds of colorectal adenomas in the United States." (PMID 20534171, 2010). "Another meta-analysis suggested that smoking may interact with certain gene variants, such as the NQO1 genetic variant, in the development of colorectal adenomas." (PMID 23226745, 2012).
coronary artery disease (5 papers, 2017 to 2025). "In murine models of coronary heart disease, addition of EGCG activates the Nrf2/HO-1/NQO1 pathway restoring protein expression of Nrf2, HO-1, and NQO1, thereby reducing cardiac tissue damage." (PMID 41226835, 2025).
esophageal cancer (5 papers, 2013 to 2025). A primary or metastatic malignant neoplasm involving the esophagus. "The simultaneous occurrence of this missense mutation suggests that NQO1 P115S is a critical mutational hotspot in early esophageal cancer." (PMID 39792765, 2025). "Overall, a significant association was found between the NQO1 C609T variant and esophageal cancer under a recessive model (OR = 1.647; 95% CI = 1.233-2.200)." (PMID 23497461, 2013). "In the racial subgroups, there was a statistically significant asssociation between the NQO1 polymorphism and esophageal cancer." (PMID 23497461, 2013). "Our study included eight published case-control studies about the NQO1 C609T polymorphism and esophageal cancer, including a total of 1,217 esophageal cancer patients and 1,560 controls." (PMID 23497461, 2013). "Six case-control articles reporting an association between the NQO1 C609T polymorphism and the histological type of esophageal cancer were included in our research, but their results were debatable." (PMID 23497461, 2013). "The summary result showed a significant relationship between the NQO1 C609T polymorphism and esophageal cancer from the meta-analysis of the phenotype studies." (PMID 23497461, 2013). "In summary, the present meta-analysis provides information that the NQO1 C609T polymorphism considerably increases susceptibility to or prognosis of esophageal cancer, especially in ESCC patients." (PMID 23497461, 2013). "The summary result from the meta-analysis of the phenotype studies indicated a significant relationship between the NQO1 C609T polymorphism and the histological type of esophageal cancer." (PMID 23497461, 2013). "The meta-analysis suggests that the NQO1 C609T polymorphism considerably increases the risk of esophageal cancer." (PMID 23497461, 2013). "This meta-analysis, involving a total of 1,217 esophageal cancer patients and 1,560 controls from eight case-control studies, examined the association of one polymorphisms of the NQO1 gene with esophageal cancer risk." (PMID 23497461, 2013). "Ten relevant studies describing the association between NQO1 C609T and esophageal cancer were identified." (PMID 23497461, 2013). "Many studies have been carried out to test the hypothesis that the NQO1 C609T polymorphism might be associated with the risk of esophageal cancer." (PMID 23497461, 2013). "Many studies have been carried out to test the hypothesis that the NQO1 C609T polymorphism might be linked to the risk of esophageal cancer, but the results are controversial." (PMID 23497461, 2013). "However, the results of some studies on the effect of the NQO1 C609T polymorphism on esophageal cancer are debatable." (PMID 23497461, 2013). "Third, we only considered the NQO1 C609T polymorphism in esophageal cancer." (PMID 23497461, 2013). "In addition, significant evidence was found for a correlation between the NQO1 C609T variant and esophageal cancer under the recessive model (OR = 1.647; 95%CI = 1.233-2.200)." (PMID 23497461, 2013). "Therefore, a meta-analysis of these studies was undertaken to investigate the association of the NQO1 C609T polymorphism with susceptibility to esophageal cancer." (PMID 23497461, 2013). "Microsatellite instability was positively correlated with the NQO1 mRNA expression levels in esophageal carcinoma and uveal melanoma and negatively correlated with uveal melanoma, invasive breast carcinoma, pan-kidney cohort, prostate adenocarcinoma, and ovarian serous cystadenocarcinoma." (PMID 37583897, 2023).
steatosis (5 papers, 2015 to 2023). Increased lipid within the cytoplasm of cells. "Thus, we consider that suppressed expression of lipogenesis-related enzymes (i.e., ACC1 and FASN) in the livers of pCAG DA-Nrf2 and pCAG Nqo1 treated RosaNIC/NIC::AdiCre mice is a part of the multifactorial mechanisms underlying improvement of steatosis in the setting of lipodystrophy." (PMID 37686150, 2023). "Therefore, activating NRF2 signaling or direct elevation of NQO1 in the liver provides new possibilities to partially reduce steatosis that accompanies lipodystrophy." (PMID 37686150, 2023). "Metabolomics analysis revealed the release of different lipid classes in the serum (e.g., PUFAs, hydroxy-fatty acids) by the adipose tissue that could, in principle, be better processed and fully oxidized in the liver, which in turn reduces steatosis and hepatic inflammation in NQO1-Tg mice." (PMID 33298924, 2020). "Compared with the control group, Nqo1, Atf3, and Cdkn1a were up-regulated in MCD diet-fed mice, and gradually increased with the aggravation of steatosis and inflammation." (PMID 37305039, 2023).